PPP3R1 (protein phosphatase 3 regulatory subunit B, alpha)
Description:
Regulatory subunit of calcineurin, a calcium-dependent, calmodulin stimulated protein phosphatase. Confers calcium sensitivity.
Synonyms: CNB; CALNB1; CNB1
Tractability: Small molecule: a structure with a bound ligand is known; it has a binding pocket of medium quality. Antibody: UniProt places it where antibodies can reach, with high confidence; its Gene Ontology location is reachable by antibodies, with medium confidence; the Human Protein Atlas places it where antibodies can reach. PROTAC: ubiquitination databases record sites on it; its protein half-life has been measured.
Target class: Protein phosphatase regulatory subunit; Phosphatase; Enzyme; Protein Phosphatase
Gene: Protein-coding gene on chromosome 2 (68,178,857 to 68,256,237, reverse strand). Ensembl gene ENSG00000221823.
Subcellular location: Cytoplasm, cytosol; Cell membrane; Cell membrane, sarcolemma
Subcellular location (Human Protein Atlas): Plasma membrane; Cytosol; Primary cilium
Pathways (Reactome):
Immune System: CLEC7A (Dectin-1) induces NFAT activation; Calcineurin activates NFAT; FCERI mediated Ca+2 mobilization
Signal Transduction: Ca2+ pathway; DARPP-32 events
Programmed Cell Death: Activation of BAD and translocation to mitochondria
Gene Ontology:
Molecular function: phosphatase binding; protein binding; protein domain specific binding; calcium ion binding; calcium-dependent protein serine/threonine phosphatase activity; calcium-dependent protein serine/threonine phosphatase regulator activity; calmodulin binding; phosphoprotein phosphatase activity
Biological process: calcineurin-NFAT signaling cascade; positive regulation of transcription by RNA polymerase II; negative regulation of calcium ion import across plasma membrane; positive regulation of calcineurin-NFAT signaling cascade; positive regulation of calcium ion import across plasma membrane; postsynaptic modulation of chemical synaptic transmission; regulation of postsynaptic neurotransmitter receptor internalization; regulation of synaptic vesicle cycle
Cellular component: calcineurin complex; plasma membrane; cytosol; nucleoplasm; protein serine/threonine phosphatase complex; glutamatergic synapse; hippocampal mossy fiber to CA3 synapse; parallel fiber to Purkinje cell synapse; postsynapse; sarcolemma; Schaffer collateral - CA1 synapse; synapse
Genetic constraint (gnomAD): Loss-of-function variants: 5 observed, 15.53 expected, observed/expected ratio (o/e) 0.32, 90% interval 0.17 to 0.68. The upper end of that interval is the gene's LOEUF score, 0.68, which puts it in group 2 of 6, group 1 being the genes least tolerant of losing a copy. Missense variants: 58 observed, 195.51 expected, observed/expected ratio (o/e) 0.3, 90% interval 0.24 to 0.37. Synonymous variants: 55 observed, 65.69 expected, observed/expected ratio (o/e) 0.84, 90% interval 0.67 to 1.05.
Homologues: Orthologues: mouse Ppp3r1 (100% identical), tropical clawed frog ppp3r1 (100% identical), dog PPP3R1 (99% identical), guinea pig PPP3R1 (99% identical), pig PPP3R1 (99% identical), rabbit PPP3R1 (99% identical), zebrafish ppp3r1a (99% identical), macaque PPP3R1 (92% identical), Drosophila melanogaster CanB2 (88% identical), Drosophila melanogaster CanB (86% identical), Caenorhabditis elegans cnb-1 (79% identical). Paralogues in human: PPP3R2 (84% identical), CHP1 (46% identical), CHP2 (37% identical), TESC (31% identical), CIB3 (29% identical), CIB1 (28% identical), CIB2 (28% identical), CIB4 (25% identical).
Diseases named in the same sentence as PPP3R1 in open-access papers:
PPP3R1 is named in the same sentence as 45 diseases in open-access papers, as found by Europe PMC text mining. Sharing a sentence is not in itself a finding about the gene and the disease. The quoted sentences say what the papers report.
Hypertension (5 papers, 2019 to 2025). The presence of chronic increased pressure in the systemic arterial system. "Previous studies have associated the PPP3R1 5I/5D polymorphism with left ventricular mass in adults exposed either to the long-term effects of hypertension or to sports training, i.e., environmental factors with a documented ability to both activate calcineurin and induce myocardial hypertrophy." (PMID 37239086, 2023). "Given these intricate cross talks and overlaps between the calcineurin pathways, hypertension signaling and the association of calcineurin, renin and antihypertensive medications, the elucidation of the exact mechanisms of WDR92/PPP3R1 region is warranted." (PMID 31754133, 2019). "A variety of statistically significant genetic polymorphisms were identified that can be attributed to the heritability of varicose veins affecting inflammation and immunity (eg, PPP3R1, EBF1, and GATA2), hypertension (eg, CASZ1), and vascular architecture (eg, CASZ1, PIEZO1, and STIM2)." (PMID 41391741, 2025).
depression (4 papers, 2019 to 2024). "In the search of an explanatory model for the observed associations between depression and the blood levels of PPP3R1, CD63, and ASGR1, platelets emerge as potentially pivotal players." (PMID 38812487, 2024). "Our differential expression analyses of gene-related probes showed nominal upregulation in depression for PPP3R1, which was replicated in both GSE53987 (prefrontal cortex) and GSE64930 (whole blood), consistent with the upregulation observed in the PSY cohort." (PMID 38812487, 2024). "Our finding with regard to PPP3R1 also support the role of the prefrontal cortex in depression and reinforces the significance of investigating PFC-related mechanisms in depression." (PMID 38812487, 2024). "The differential expression of PPP3R1 in the prefrontal cortex of depressed adolescents aligns with the existing evidence that the PFC is one of the regions most consistently affected in depression." (PMID 38812487, 2024). "Our study of adolescent depression revealed protein-level and transcriptomic differences, particularly in PPP3R1, pointing to the involvement of the calcineurin pathway in depression." (PMID 38812487, 2024). "Our findings regarding PPP3R1 also support the role of the prefrontal cortex in depression and reinforce the significance of investigating prefrontal cortex-related mechanisms in depression." (PMID 38812487, 2024). "Our study on adolescent depression revealed protein-level and transcriptomic differences, particularly in PPP3R1, pointing to the involvement of the calcineurin pathway in depression." (PMID 38812487, 2024). "For example, the low pH/high lactate group included SZ model Nrgn KO mice, SZ/intellectual disability (ID) models Ppp3r1 KO mice and Hivep2 (also known as Shn2) KO mice, AD model APP-J20 Tg mice, ASD model Chd8 KO mice, and social defeat stress-induced depression model mice." (PMID 38529532, 2024).
cardiac hypertrophy (3 papers, 2016 to 2023). "Studies have also shown polymorphisms in PPP3R1 to be associated with ventricular hypertrophy in AA hypertensive patients." (PMID 31754133, 2019). "The predictive activities of the differential trend between PPP3CB and PPP3R1 to the Role of NFAT in cardiac hypertrophy pathway implicated activation of this pathway." (PMID 27907007, 2016). "Therefore, we focused on deciphering and discussing their regulatory roles in cardiac hypertrophy in the following sections and 5 focused NFAT associated genes (PLCE1, PPP3R1, PPP3CB, CAMK1, MEF2C) were studies for experimental validation." (PMID 27907007, 2016). "Notably, the expression patterns of PPP3CB, PPP3R1, PLCE1, MEF2C and CAMK1 in the “NFAT in cardiac hypertrophy” pathway played a significant role in the activation of hypertrophy of atrial myocytes in MR patients compared to normal subjects." (PMID 27907007, 2016).
left ventricular hypertrophy (3 papers, 2016 to 2023). Enlargement of the LEFT VENTRICLE of the heart. "Specifically with respect to PPP3R1, HYPER-GEN sub study found a novel 5 base pair deletion in the PPP3R1 promoter region to be significantly associated with left ventricular hypertrophy in severe hypertensive African American patients." (PMID 31754133, 2019). "Overexpression of PPP3R1, also known as modulatory calcineurin-interacting protein-1, has been reported to attenuate left ventricular hypertrophy after myocardial infarction." (PMID 27907007, 2016).
Alzheimer disease (2 papers, 2018 to 2020). A progressive, neurodegenerative disease characterized by loss of function and death of nerve cells in several areas of the brain leading to loss of cognitive function such as memory and language. "PPP3R1 was reported to participate in several biological processes such as improve therapeutic strategy to treat autoimmune disorders and neurological disorders such as Alzheimer disease either responses of skeletal muscle and cardiac muscle." (PMID 29301573, 2018).
breast cancer (2 papers, 2015 to 2022). A primary or metastatic malignant neoplasm involving the breast. "The calcineurin regulatory subunit PPP3R1 shows elevated expression in ER− breast cancer, whereas positive regulators of Rag C/D, including folliculin complex members FLCN and FNIP1, along with MAP4K3, are decreased in ER− breast cancer patients." (PMID 36372230, 2022).
gastric cancer (2 papers, 2021 to 2024). A primary or metastatic malignant neoplasm involving the stomach.
Anxiety (1 paper, 2025). Intense feelings of nervousness, tension, or panic often arise in response to interpersonal stresses. "This may account for higher male baseline expression of genes such as Atp1a2, Ppp3r1, and Nrn1, and a lack of an Egr1 effect on the expression of these genes and related phenotypes, such as anxiety-related behaviour, due to a possible ceiling effect in males." (PMID 41390827, 2025).
autoimmune disease (1 paper, 2023). A disorder resulting from loss of function or tissue destruction of an organ or multiple organs, arising from humoral or cellular immune responses of the individual to their own tissue constituents. "Moreover, miR-548a-3p has been involved in keratinocyte proliferation by targeting PPP3R1 and T regulatory cells, pointing out a possible implication in the pathogenesis of psoriasis, a T cell-mediated autoimmune disease." (PMID 37254147, 2023).
colorectal cancer (1 paper, 2024). A primary or metastatic malignant neoplasm that affects the colon or rectum. "As one of immune related gene signatures, overexpression of PPP3R1 was also associated with poor prognosis of colorectal cancer patients." (PMID 38467827, 2024).
coronary artery disease (1 paper, 2020). "The elevated serum calcineurin levels has been found in the early onset of coronary artery disease and was associated with the polymorphism at the promoter region on PPP3R1(Protein Phosphatase 3, Regulatory Subunit B, Alpha)." (PMID 32183825, 2020).
dementia (1 paper, 2013). Loss of intellectual abilities interfering with an individual's social and occupational functions. "MAPT and PPP3R1 also showed weak associations with clinical AD, which suggest that they contribute to dementia risk." (PMID 23573206, 2013).
epilepsy (1 paper, 2017). A brain disorder characterized by episodes of abnormally increased neuronal discharge resulting in transient episodes of sensory or motor neurological dysfunction, or psychic dysfunction. "The brown module has 53 hub genes, including genes associated with dopaminergic signaling (GNB1, GSK3B), long-term potentiation (PPP1CB), opioid signaling (PPP2CA, PPP3CA, PPP3R1), epilepsy (SYN1), and Parkinson’s disease (SNCA)." (PMID 28710498, 2017).
Hypercholesterolemia (1 paper, 2018). An increased concentration of cholesterol in the blood. "Here we predicted in silico that Ppp3r1 mRNA is significantly suppressed by 6 upregulated miRNAs (predominantly by the miR-30 family) in hypercholesterolemia." (PMID 29973623, 2018). "The comprehensive and unbiased bioinformatic analysis of the miRNA-mRNA interactome revealed that both the mRNA and the protein product of Adrb2 gene, as well as PPP3R1 protein are decreased in hypercholesterolemia." (PMID 29973623, 2018). "The expression of Adrb2 mRNA was significantly downregulated in hypercholesterolemia compared to the normocholesterolemic group, however, mRNA expression of Ppp3r1 and Cask was not affected." (PMID 29973623, 2018). "Indeed, although the expression of Ppp3r1 mRNA was not decreased by hypercholesterolemia, the CNB1 protein (translational product of Ppp3r1 mRNA) was significantly downregulated." (PMID 29973623, 2018).
lung adenocarcinoma (1 paper, 2022). A carcinoma that arises from the lung and is characterized by the presence of malignant glandular epithelial cells. "A study of survival-associated lung adenocarcinoma gene signatures found PPP3R1 as one of 10 survival-associated genes, exhibiting an inverse association between mRNA levels and risk of death; that is, the higher the expression, the lower the risk of death." (PMID 36553541, 2022). "Furthermore, by RNA-Seq, a fusion between PPP3R1 and CNRIP1 genes was observed both in noninvolved tissue and in lung adenocarcinoma tissue." (PMID 36553541, 2022).
neuroblastoma (1 paper, 2014). Neuroblastoma (NB) is the most common solid, extracranial childhood tumor. "siRNA mediated knockdown of PPP3R1 (Protein phosphatase 3 (formerly 2B), regulatory subunit B, alpha isoform) found to increase α-syn S129 phosphorylation levels in neuroblastoma derived cells." (PMID 25426138, 2014). "siRNA mediated knockdown of PPP3R1 (Protein tyrosine phosphatase, receptor type, A) reported to decrease α-syn S129 phosphorylation levels in neuroblastoma derived cells." (PMID 25426138, 2014).
pregnancy disorder (1 paper, 2024). A disorder that is related to pregnancy. "Moreover, in relation to pregnancy disorders, ATP2B4 had decreased mRNA and protein levels in syncytiotrophoblasts cultured from preeclamptic placental tissue, whereas PPP3R1 mRNA levels were increased in PE-associated placentas." (PMID 38455065, 2024).
tumor (10 papers, 2015 to 2024). "qPCR experiments verified that the expressions of MAP7, CDK1, PPP3R1, PRKC1, CCND1 and HDAC1 genes were indeed altered in AT/RT tumor tissue." (PMID 35524230, 2022). "However, the analysis of LSCC specimens did not reveal significant correlations of either PPP3R1 or PPP1CC with the prognosis or tumor malignancy (data not shown), while an increased PIK3CD expression was significantly correlated with tumor progression and the clinical outcomes." (PMID 32555190, 2020).
cancer (6 papers, 2009 to 2024). A tumor composed of atypical neoplastic, often pleomorphic cells that invade other tissues. "It was worth noting that the expression levels of CXCR4, PPP3R1, HSP90AB1, CXCL10, and S100A12 were substantially elevated in multiple types of cancer tissues." (PMID 36569892, 2022).
infectious disease (1 paper, 2010). A disorder directly resulting from the presence and activity of a microbial, viral, or parasitic agent in humans. "We observed that top functions these genes involved are RNA post-Transcriptional Modification (CLP1 TSEN2 and TSEN54) and infectious disease and inflammatory disease (NR3C1, PPP3CC, and PPP3R1)." (PMID 21172007, 2010).
PPP3R1 also shares sentences with these, for which no sentence is quoted: infection (2 papers); Obesity (2); aortic valve disease (1); Chronic colitis (1); colitis (1); dengue (1); diabetes (1); hematological disease (1); inflammation (1); Intellectual disability (1); Jaundice (1); learning disorders (1); leprosy (1); melanoma (1); myocardial infarction (1); neurological disorders (1); Parkinson disease (1); preeclampsia (1); psoriasis (1); sarcoma (1); skin inflammation (1); skin tumors (1); squamous cell carcinoma (1); Varicose veins (1); Ventricular hypertrophy (1).